RNU6-151P (RNA, U6 small nuclear 151, pseudogene)
Gene: Small nuclear RNA gene on chromosome 1 (111,650,431 to 111,650,537, reverse strand). Ensembl gene ENSG00000201028.
Homologues: Orthologues: chimpanzee U6 (99% identical), macaque U6 (94% identical), guinea pig U6 (76% identical), rabbit U6 (71% identical). Paralogues in human: RNU6-1145P (89% identical), RNU6-393P (89% identical), RNU6-480P (89% identical), RNU6-1209P (88% identical), RNU6-1316P (88% identical), RNU6-345P (88% identical), RNU6-742P (88% identical), RNU6-1067P (87% identical), RNU6-1181P (87% identical), RNU6-16P (87% identical), RNU6-29P (87% identical), RNU6-38P (87% identical), and 1287 more.